TMEM219 (transmembrane protein 219)
Diseases named in the same sentence as TMEM219 in open-access papers:
TMEM219 is named in the same sentence as 35 diseases in open-access papers, as found by Europe PMC text mining. Sharing a sentence is not in itself a finding about the gene and the disease. The quoted sentences say what the papers report.
melanoma (4 papers, 2016 to 2022). A malignant, usually aggressive tumor composed of atypical, neoplastic melanocytes. "Null mutations of TMEM219 or IL-13Rα2 also phenocopied one another as regards the ability of Chi3l1 to inhibit oxidant-induced apoptosis and lung injury, promote melanoma metastasis and stimulate TGF-β1." (PMID 27629921, 2016). "Melanoma cell administration caused impressive levels of metastasis in lungs from WT mice and this metastatic response was markedly decreased in lungs from TMEM219−/− mice." (PMID 27629921, 2016). "The CHI3L1/IL‐13Rα2 complex accompanied by TMEM219 promotes oxidant‐induced apoptosis, lung injury, and melanoma metastasis through activation of the macrophage ERK/AKT pathway." (PMID 34758182, 2022). "Prior studies from our laboratory and the present investigations demonstrate that IL-13Rα2 and TMEM219 play critical roles in melanoma metastasis." (PMID 27629921, 2016). "Here, the authors show that TMEM219 is a IL-13Rα2 co-receptor and modulates oxidant-induced apoptosis and lung injury, melanoma metastasis and TGF-β1 signalling, downstream of Chi3l1-IL-13Rα2." (PMID 27629921, 2016). "Notably, the CHI3L1/IL-13R2 (its receptor) complex and transmembrane protein 219 (TMEM219) exacerbate lung damage, melanoma metastasis, and oxidant-induced apoptosis by activating the AKT pathway." (PMID 36615523, 2022). "The present studies demonstrate that mice that lack IL-13Rα2 or TMEM219 manifest similar increases in IgE production and Th2 cytokine elaboration and similar decreases in MAPK and Akt signalling and melanoma metastasis." (PMID 27629921, 2016). "To accomplish this, we compared the metastasis of B16-F10 melanoma cells and the TGF-β1 that they induce in WT mice and TMEM219 null mice." (PMID 27629921, 2016).
breast carcinoma (2 papers, 2020 to 2022). "Confirming our previous observations, the survival benefits of IGFBP-3 expression in breast cancer were consistently associated with high IGFBP-3 expression, while the effect of TMEM219 was more diverse and subgroup-specific." (PMID 32443727, 2020). "The following genes were reported to be higher expressed in breast cancer samples of cases compared to controls in two different studies but were reported to be lower expressed in another study: SFRP1, ACTR1B, FASTK, TMEM219, NDUFA3, ATP5I." (PMID 36627894, 2022).
Crohn disease (2 papers, 2025). A gastrointestinal disorder characterized by chronic inflammation involving all layers of the intestinal wall, noncaseating granulomas affecting the intestinal wall and regional lymph nodes, and transmural fibrosis. "Mechanistic studies revealed a proapoptotic TMEM219-mediated molecular signature in Crohn’s disease, which associates with Caspase-8 activation and ISC death." (PMID 40371646, 2025). "Targeting TMEM219 using ecto-TMEM219 restored the self-renewal abilities of mini-guts generated from patients with Crohn’s disease in vitro." (PMID 40371644, 2025). "Moreover, in a cohort of patients with a refractory course of Crohn’s disease or active Crohn’s disease, TMEM219 signaling was activated and correlated with a failure of mucosal regeneration." (PMID 40371644, 2025). "Herein, we report an abnormal ISC death that occurs in Crohn’s disease, which exacerbates colitis, limits ISC-dependent mucosal repair, and is controlled through the death factor Transmembrane protein 219 (TMEM219)." (PMID 40371646, 2025).
diabetes (2 papers, 2022 to 2025). "The observation that IGFBP3 levels are increased in patients with T1D or T2D and in those at risk for developing diabetes, as well as in pre-diabetic and diabetic mice, suggests a dysregulation of the IGFBP3/TMEM219 pathway in the context of diabetes." (PMID 35115561, 2022). "We therefore interrogated the role of the IGFBP3/TMEM219 axis and its targeting in well-renown in vivo models of diabetes." (PMID 35115561, 2022). "IGFBP3/TMEM219 blockade with ecto-TMEM219 prevented the onset of diabetes in nearly 75% of treated mice (up to 80%), while only 25% of control mice were protected from diabetes in the untreated group." (PMID 35115561, 2022). "In this new study the Authors demonstrated that the IGFBP3/TMEM219 pathway is a physiological regulator of pancreatic beta cell homeostasis and it is dysregulated in diabetes." (PMID 35115561, 2022). "Reduced IGFBP3 plasma levels and preserved islet morphology further confirmed the beneficial effect of ecto-TMEM219-mediated IGFBP3 inhibition in this diabetes model." (PMID 35115561, 2022). "Pharmacological or genetic targeting of the IGFBP3/TMEM219 pathway successfully protects beta-cell mass, facilitates beta-cell expansion, and prevents and delays diabetes onset, suggesting a new therapeutic option for diabetic patients." (PMID 35115561, 2022). "In vitro and in vivo short-term IGFBP3/TMEM219 inhibition and TMEM219 genetic ablation preserved beta cells and prevented/delayed diabetes onset, while long-term IGFBP3/TMEM219 blockade allowed for beta cell expansion." (PMID 35115561, 2022). "Pharmacological disruption of this axis using the extracellular domain of TMEM219 (ecto-TMEM219) provides temporally distinct benefits in preclinical diabetes models by initially enhancing beta-cell survival and preventing diabetes onset and promoting beta-cell expansion in the long-term." (PMID 40612435, 2025). "The increased hepatic production of IGFBP3 observed in vitro upon exposure to either T1D or T2D serum and the abrogation obtained by targeting the pro-inflammatory microenvironment further suggest a common path of dysregulation for the IGFBP3/TMEM219 axis in diabetes." (PMID 35115561, 2022). "Overall, our findings demonstrate that the IGFBP3/TMEM219 pathway may serve as a physiological controller of beta cells and their lifespan, and that this pathway is dysregulated in diabetes." (PMID 35115561, 2022). "More importantly, the use of a newly generated recombinant protein based on the TMEM219 extracellular domain (ecto-TMEM219), which inhibits the IGFBP3/TMEM219 pathway, protected beta cells in vitro and prevented the onset of hyperglycemia in murine models of diabetes in vivo." (PMID 35115561, 2022). "IGFBP3/TMEM219 targeting may therefore serve as a therapeutic option in diabetes." (PMID 35115561, 2022).
inflammatory bowel disease (2 papers, 2025). A spectrum of small and large bowel inflammatory diseases of unknown etiology. "Our study showed that a TMEM219-dependent intestinal stem cells death exacerbates colitis and that TMEM219 blockade re-establishes intestinal self-renewal properties in inflammatory bowel disease." (PMID 40371646, 2025).
schizophrenia (2 papers, 2021 to 2022). A major psychotic disorder characterized by abnormalities in the perception or expression of reality. "The TMEM219 gene is located in a multigenetic copy number variation region (16p11.2) associated with several brain disorders, including schizophrenia, seizure, and Alzheimer’s disease." (PMID 36011399, 2022). "The predicted expression of INO80E and TMEM219 from the discovery analyses were associated (P < 0.05) with having an ICD10 diagnosis of schizophrenia (ICD10: F20, 198 cases: INO80E P = 0.04, TMEM219 P = 0.03)." (PMID 34715901, 2021). "Two genes at 16p11.2 show predicted expression positively associated (P < 7.9 × 10−5) with schizophrenia: TMEM219 (P = 1.5 × 10−5) and INO80E (P = 5.3 × 10−10)." (PMID 34715901, 2021).
bladder urothelial carcinoma (1 paper, 2020). "Higher TMEM219 expression was associated with better survival in bladder urothelial carcinoma (FDR = 9.54∙10−3 (HR = 0.61)), while the reverse was true for head and neck squamous cell carcinoma (FDR = 4.17∙10−2 (HR = 1.43))." (PMID 32443727, 2020). "In addition to the cancer types expected to be affected by the IGFBP-3/TMEM219 system, bladder urothelial carcinoma and head and neck squamous cell carcinoma appear to be significantly associated with TMEM219 but not with IGFBP-3 expression." (PMID 32443727, 2020).
Chronic colitis (1 paper, 2025). A chronic inflammatory disease of the large intestine (colon, cecum and rectum). "Genetic and pharmacological blockade of the IGFBP3/TMEM219 signaling successfully preserved ISCs and their self-renewal properties in vitro, enabled proliferation and recovery of intestinal crypts, and ameliorated the signs and symptoms of acute and chronic colitis in preclinical models in vivo." (PMID 40371646, 2025). "Pharmacological blockade of IGFBP3/TMEM219 signal ameliorates DSS-mediated acute and chronic colitis in vivo." (PMID 40371646, 2025). "To further test IGFBP3/TMEM219 blockade in a model that better mimics the chronic inflammation of CD, we used the DSS-mediated chronic colitis treatment model, in which colitis was induced with 3 cycles of oral DSS and ecto-TMEM219 was started after the colitis establishment at day +18." (PMID 40371646, 2025).
colitis (1 paper, 2025). Inflammation of the colon. "Finally, genetic inhibition of TMEM219 was associated with an improvement in signs and symptoms of colitis, with reduced infiltration of immune cells." (PMID 40371646, 2025). "Remarkably, in the T cell transfer model, which closely mimics features and development of CD, TMEM219 blockade delayed the disease onset, reduced the colitis severity, and promoted mucosal repair." (PMID 40371646, 2025). "The relevance of the IGFBP3/TMEM219 axis in reducing gut inflammation has also been confirmed in the IGFBP3–/– mice that were protected from DSS-mediated colitis." (PMID 40371646, 2025). "Our findings demonstrate that a TMEM219-dependent ISC death exacerbates colitis and that TMEM219 blockade reestablishes intestinal self-renewal properties in IBD." (PMID 40371646, 2025). "We also confirmed the effect of pharmacological blockade of the IGFBP3/TMEM219 signaling/binding in vivo in a DSS-induced acute colitis treatment approach, in which colitis was established first and administration of ecto-TMEM219 was then started at day +3." (PMID 40371646, 2025). "Overall, these results indicate that pharmacological blockade of the IGFBP3/TMEM219 signaling/binding with ecto-TMEM219 in vivo ameliorates signs and symptoms of acute colitis and preserves intestinal immune homeostasis." (PMID 40371646, 2025). "In vivo, abrogation of TMEM219-mediated cell death in acute and chronic DSS–induced colitis using a preventive/curative approach was associated with near normalization of mucosal morphology and ISC regenerative function." (PMID 40371646, 2025). "An improvement in the colitis severity and stool consistency score was observed in animals treated with ecto-TMEM219 at the endoscopic analysis accounting for a decrease in the colitis score." (PMID 40371646, 2025). "Pharmacological blockade of IGFBP3/TMEM219 signal improves colitis in a T cell adoptive transfer model." (PMID 40371646, 2025). "To strengthen our findings, we demonstrated in a proof-of-concept study that pharmacological blockade of the IGFBP3/TMEM219 signaling/binding with ecto-TMEM219 successfully improved the signs and symptoms of colitis in a T cell adoptive transfer model, which better parallels the pathogenesis of CD." (PMID 40371646, 2025). "Notably, direct inhibition of TMEM219 with a newly generated anti-TMEM219 monoclonal antibody improved colitis phenotype and disease activity." (PMID 40371646, 2025). "This study demonstrates the existence of an abnormal TMEM219-mediated ISC death in CD, which exacerbates colitis, limits ISC-dependent mucosal repair, and acts by activating the Caspase-8 signaling." (PMID 40371646, 2025). "We used a Dextran Sodium Sulfate–induced (DSS-induced) acute colitis mouse model, in which DSS was orally administered for 5 days, and ecto-TMEM219 was administered starting at day –3 in a preventive approach." (PMID 40371646, 2025). "In this study, we demonstrated the existence of an abnormal ISC death in CD, which exacerbates colitis, limits ISC-dependent mucosal repair, and is controlled through the death factor TMEM219." (PMID 40371646, 2025). "We finally tested whether Tmem219 genetic deletion in the ISC-Tmem219–/– mice was effective in a treatment model, in which 2.5% DSS was orally administered for 5 days and Tmem219 genetic deletion was induced after the onset of colitis." (PMID 40371646, 2025).
endometrial tumour (1 paper, 2024). "In contrast, of the more highly expressed genes in normal tissue, all except TMEM219 and PRRT2 had a gene dosage effect in endometrial tumour tissue (p < 0.0001)." (PMID 39495297, 2024).
enteritis (1 paper, 2025). Inflammation of the small intestine. "To further support the relevance of deleting TMEM219 in ISCs in an immune-mediated enteritis model, we administered a Toll-like receptor–3 agonist, (Poly I:C), which activates immune response, in the ISC-Tmem219–/– and ISC-B6 mice in a preventive approach using a short-term protocol." (PMID 40371646, 2025). "Weight loss was less evident while leukocyte infiltration was significantly reduced in the ISC-Tmem219–/– compared with the ISC-B6 mice, thereby confirming a beneficial effect of TMEM219 abrogation also in a different enteritis model." (PMID 40371646, 2025).
glioblastoma (1 paper, 2019). The most malignant astrocytic tumor (WHO grade IV). "Literature review helped us identify potential binding partners (CRTH2, TMEM219, and IL13Rα2) and their expression in both non-neoplastic and glioblastoma tissue was analyzed based on data from The Cancer Genome Atlas Program (TCGA) database." (PMID 31561550, 2019). "While CHI3L1 significantly impacts the survival of glioblastoma patients, TMEM219 did not affect overall survival." (PMID 31561550, 2019).
Hermansky-Pudlak syndrome (1 paper, 2025). Hermansky-Pudlak syndrome (HSP) is a multi-system disorder characterized by oculocutaneous albinism, bleeding diathesis and, in some cases, neutropenia, pulmonary fibrosis, or granulomatous colitis. "In Hermansky-Pudlak Syndrome lung disease, galectin-3 competes directly with TMEM219 to bind IL13RA2." (PMID 40663259, 2025).
insulinoma (1 paper, 2024). "To better understand the link between TMEM219 signal and proliferation of beta cell precursors, we took advantage of samples obtained from patients with insulinoma, in which pancreatic beta cells are prone-to-proliferate." (PMID 38318298, 2024). "miR-129-2 mimic downregulated TMEM219 expression in islets, in in vitro embryonic-derived endocrine progenitors and in highly proliferating insulinoma-derived cells." (PMID 38318298, 2024). "Interestingly, when testing miR-129-2 transfection in the insulinoma cell line, we confirmed a decrease in the expression of TMEM219, but more remarkably we detected an increase in MKI67 and Insulin mRNA levels." (PMID 38318298, 2024). "Moreover, miR-129-2 inhibitor induced a TMEM219 overexpression in insulinoma-derived cells, which restored cell proliferation and functional markers, thus acting as endogenous regulator of TMEM219 expression." (PMID 38318298, 2024).
nesidioblastosis (1 paper, 2022). "Of note, prolonged IGFBP3/TMEM219 blockade with ecto-TMEM219 was associated with significant beta-cell expansion, which lead to a significant increase of both islet area and peripheral insulin levels, mimicking nesidioblastosis." (PMID 35115561, 2022). "Interestingly, prolonged inhibition of TMEM219 signaling using ecto-TMEM219 treatment appeared to prevent normal beta-cell turnover and increased peripheral insulin levels to the point that the beta-cell mass markedly expanded, almost mimicking nesidioblastosis." (PMID 35115561, 2022).
type 1 diabetes (1 paper, 2024). "While addressing the upstream controlling TMEM219 expression, we determined the TMEM219 miRNet; indeed, one of those miRNAs, miR-129-2, is highly expressed in human islets, particularly in patients at risk or with established type 1 diabetes." (PMID 38318298, 2024). "The TMEM219 upstream regulator miR129-2 controls the fate of beta cell precursors and may unleash their regenerative potentials to replenish beta cells in type 1 diabetes." (PMID 38318298, 2024). "While in pathological conditions such as type 1 diabetes, the TMEM219 signaling is abnormally activated and it highly contributes to beta cell loss and dysfunction, in physiological conditions, TMEM219 acts mainly as a death receptor that regulates cells homeostasis and lifecycle." (PMID 38318298, 2024).
tumor (6 papers, 2016 to 2025). "Among them, TMEM219 appears to be the most critical IGFBP-3 receptor mediating anti-tumor and anti-metastatic activities of IGFBP-3." (PMID 32443727, 2020). "The remainder of this review will focus on the IGFBP-3 receptor TMEM219 in human cancer by mainly providing the evidence to date regarding the IGFBP-3/TMEM219 system as an anti-tumor and anti-metastatic signaling in human cancer." (PMID 32443727, 2020). "Seven-mutated genes detected from bcWES data are detected in single cells of either primary tumor or lymph node (fdr2d<0.2): MT-RNR2, MT-RNR1, MT-ND5, MT-TI, HUWE1, TMEM219 and INTS8." (PMID 31028395, 2019).
cancer (4 papers, 2017 to 2025). A tumor composed of atypical neoplastic, often pleomorphic cells that invade other tissues. "This approach allowed us to understand the effect of IGFBP3 and TMEM219 expression on the level of individual cancers and in specific population subgroups." (PMID 32443727, 2020). "In addition, CHI3L1 binds to a receptor complex consisting of TMEM219 and CD44v3, activating pathways like AKT, MAPK (p42/p44), and β-catenin, thereby promoting tumorigenesis, particularly in cancer cells and cancer-associated fibroblasts." (PMID 40643503, 2025). "Further characterization of specific gene regulation by TMEM219 activation and its crosstalk with other key signaling pathways will open a new avenue to treat many different types of cancer as a targeted monotherapy and a combination therapy with other chemotherapies." (PMID 32443727, 2020). "In the same datasets, TMEM219 expression also showed variable expression patterns, but had less variation when compared to IGFBP-3 among different types of cancer as well as normal tissues." (PMID 32443727, 2020).
TMEM219 also shares sentences with these, for which no sentence is quoted: Alzheimer disease (1 paper); brain disorder (1); breast invasive carcinoma (1); dental caries (1); glioma (1); head and neck squamous cell carcinoma (1); Hyperglycemia (1); Lobular Carcinoma (1); lung carcinoma (1); lung disease (1); lung injury (1); oral cancer (1); periodontitis (1); prostate adenocarcinoma (1); prostate carcinoma (1); type 2 diabetes (1); uterine corpus endometrial carcinoma (1).